LINC00402 (long independently transcribed non-coding RNA 402)
Synonyms: LINC00381; LOC105370259
Gene: Long non-coding RNA gene on chromosome 13 (74,231,401 to 74,555,515, forward strand). Ensembl gene ENSG00000235532.
Diseases named in the same sentence as LINC00402 in open-access papers:
LINC00402 is named in the same sentence as 4 diseases in open-access papers, as found by Europe PMC text mining. Sharing a sentence is not in itself a finding about the gene and the disease. The quoted sentences say what the papers report.
colon cancer (2 papers, 2020 to 2021). "In colon cancer, LINC00402 competitively binds miR-141 and miR-424 as the ceRNA of PHLPP2, and LINC00402 has also been confirmed to be associated with metastatic melanoma." (PMID 34324544, 2021). "The upregulation of LINC00402, LINC00461, and SFTA1P was verified to enhance the suppressive effects of PHLPP2 in the pathogenesis of colon cancer." (PMID 32633726, 2020).
metastatic melanoma (2 papers, 2021 to 2024). A melanoma that has spread from its primary site to another anatomic site. "Six of these lncRNAs - AC068594.1, C7orf71, FAM41C, GPC5-AS1, MUC19, and LINC00402 - were correlated with survival time in metastatic melanoma patients." (PMID 39764216, 2024).
tumor (2 papers, 2020 to 2022). "In the prognostic PRlncRNA risk model, 8 lncRNAs (HOTAIR, LINC00402, SFTA1P, LINC00461, DSCR8, CYP1B1-AS1, LINC00330, ALMS1-IT1) were upregulated, while the other 3 lncRNAs (ZRANB2-AS1, MYB-AS1, TP53TG1) were downregulated in tumor tissues." (PMID 35413978, 2022). "HE staining also demonstrated that overexpression of LINC00402, LINC00461, and SFTA1P could enhance the inhibitory effect of PHLPP2 on tumor formation and metastasis." (PMID 32633726, 2020). "The results also confirmed overexpression of LINC00402, LINC00461, SFTA1P, and PHLPP2 or the inhibition of miR-141 and miR-424, could suppress the tumor growth (all p < 0.05)." (PMID 32633726, 2020).
cancer (1 paper, 2022). A tumor composed of atypical neoplastic, often pleomorphic cells that invade other tissues. "Among the eight lncRNA signatures, MYOSLID, AC012073.1, and LINC00402 were associated with progression in various cancer types, but there is hardly any information reported on HCC." (PMID 36147735, 2022).